SOD1 (superoxide dismutase 1)
Diseases named in the same sentence as SOD1 in open-access papers (continued):
Sharing a sentence is not in itself a finding about the gene and the disease.
sarcoma (61 papers, 2011 to 2025). A usually aggressive malignant neoplasm of the soft tissue or bone. "The most common mutations have been identified in SOD1 (superoxide dismutase 1), C9orf72 (chromosome 9 open reading frame 72), TARDBP (transactive response DNA binding protein 43), and FUS (fused in sarcoma)." (PMID 40243477, 2025). "The five most common genetic causes are hexanucleotide amplification of Chromosome 9 open reading frame 72 and superoxide dismutase 1 (SOD1), TAR DNA binding protein 43, fusion sarcoma, TANK‐binding kinase 1 mutations." (PMID 41018230, 2025). "Other mouse models of severe ALS with human TAR DNA-binding protein-43 or fused-in-sarcoma mutations also exhibit early NMJ pathology, similar to that observed in SOD1 mice." (PMID 40356623, 2025). "The mutated genes involved are genes encoding Cu/Zn superoxide dismutase (SOD1), TAR-DNA binding protein 43 (TDP-43), fused in sarcoma/translocated in liposarcoma (FUS/TLS), and C9ORF72." (PMID 38524401, 2024). "Several genes have been implicated in familial ALS, including SOD1 (superoxide dismutase 1), C9orf72 (chromosome 9 open reading frame 72), TARDBP (TAR DNA-binding protein), FUS (fused in sarcoma), and others." (PMID 39199129, 2024). "Repeat expansions in the C9ORF72 gene and mutations in superoxide dismutase 1 (SOD1) are common genetic causes of ALS, while TAR DNA-binding protein (TDP-43) and fused in sarcoma/translated in liposarcoma (FUS/TLS) mutations represent a smaller fraction." (PMID 38463392, 2024). "Aggregation of misfolded proteins due to mutation genes encoding SOD1 (superoxide dismutase 1), TDP-43 (TAR-DNA binding protein-43), and FUS/TLS (fused in sarcoma/translocated in liposarcoma) results in endoplasmic reticulum stress." (PMID 36788871, 2023). "Familial ALS is known to be caused by SOD1 (superoxide dismutase 1) and FUS (fused in sarcoma) mutations." (PMID 37545694, 2023). "Mutation in the superoxide dismutase -1 gene (SOD1), TAR-DNA binding, chromosome 9 open reading frame 72, and fused sarcoma are the main causes of familial ALS." (PMID 36297602, 2022). "The remaining cases are familial and associated with numerous genetic mutations, including C9ORF72, superoxide dismutase 1 (SOD1), TAR DNA-binding protein, fused in sarcoma, and ubiquilin-2 mutations." (PMID 35855239, 2022). "Most common are mutations in C9orf72 (chromosome 9 open reading frame 72), SOD1 (superoxide dismutase 1), FUS (fused in sarcoma), and TARDBP (encoding for TDP-43)." (PMID 35777956, 2022). "These include mutant SIGMAR1 encoding the Sigma-1 receptor, mutant SOD1 encoding Cu/Zn superoxide dismutase-1 (SOD1), mutant TARDBP encoding TDP43, mutant FUS encoding fused in sarcoma and mutant C9orf72." (PMID 35693938, 2022). "The most common genes involved are Chromosome 9 open reading frame 72 (C9orf72), SOD1, TDP-43, fused in sarcoma and TANK-binding kinase 1, which together cause 15% of the ALS cases." (PMID 36751500, 2022). "In contrast, only 10% of ALS cases have a familial background, including the most frequently mutated genes SOD1 (superoxide dismutase 1), TDP-43 (TAR DNA binding protein) and FUS (fused in sarcoma)." (PMID 34295920, 2021). "fALS is genetically linked to at least 15 genes, including SOD1 (Cu/Zn superoxide dismutase), TARDBP (TAR DNA-binding protein), FUS (fused in sarcoma), ANG (angiogenin precursor), and OPTN (optineurin)." (PMID 34876200, 2021). "In line with this, a hallmark pathology of ALS is protein deposition and inclusion formation within motor neurons and surrounding glia of the proteins TAR DNA-binding protein 43, superoxide dismutase-1, or fused in sarcoma." (PMID 33328890, 2020). "FALS occurs in mendelian-inherited mutations of the following genes: Cu/Zn superoxide dismutase (SOD1), TAR-DNA–binding protein 43 (TDP-43), fused in sarcoma/translocated in liposarcoma (FUS/TLS) and the chromosome 9 open reading frame 72 gene (C9orf72)." (PMID 31181747, 2019).
sarcoma (continued). "Several misfolded proteins have been linked to ALS, including superoxide dismutase 1 (SOD1), TAR DNA‐binding protein 43 KDa (TDP‐43) and fused in sarcoma." (PMID 25556298, 2015). "Despite the growing number and variety of these genes, four of them stand out as the most commonly mutated in ALS: superoxide dismutase 1 (SOD1), chromosome 9 open reading frame 72 (C9orf72), fused in sarcoma/translocated in liposarcoma (FUS/TLS), and TAR DNA-binding protein 43 (TARDBP-43)." (PMID 40422183, 2025). "The genetic mutations such as superoxide dismutase 1 (SOD1), TAR DNA-binding protein 43 (TDP-43) and Chromosome 9 open reading frame 72 (C9ORF72), fused in sarcoma/translocated in lip sarcoma (FUS/TLS) resulting in accumulation of misfolded proteins have been linked to the disease." (PMID 31225510, 2019). "Genetic factors, including mutations of the C9orf72, SOD1 (superoxide dismutase 1), TARDPB, or FUS (fused in sarcoma) genes, may explain almost 50% of familial cases (FALS)." (PMID 25101285, 2014). "The majority of ALS cases which have been reported are sporadic (SALS); 10% are familial (FALS), some of which arise from mutations in superoxide dismutase-1 (SOD1), TAR DNA-binding protein (TDP43) and fused in sarcoma/translated in liposarcoma (FUS/TLS), ALS2, dynactin, and senataxin." (PMID 26317018, 2013). "Sanger sequencing was used to screen these subjects for mutations in the coding regions of superoxide dismutase-1 (SOD1), angiogenin (ANG), fused in sarcoma/translated in liposarcoma (FUS/TLS), TAR DNA-binding protein 43 (TARDBP), and multivesicular body protein 2B (CHMP2B)." (PMID 23155438, 2012). "Clinically indistinguishable ALS can be caused by genetic mutations of Cu/Zn superoxide dismutase (SOD1), TAR-DNA binding protein 43 (TDP43), or fused in sarcoma/translocated in liposarcoma (FUS/TLS), or can occur in the absence of known mutation as sporadic disease." (PMID 22493728, 2012). "The main proteins involved in the onset of ALS are C9orf72, SOD1 (superoxide dismutase 1), TDP-43, and FUS (fused in sarcoma)." (PMID 40426973, 2025). "More than 20 genes have been associated with the disease, including superoxide dismutase 1 (SOD1), TAR DNA binding protein (TARDBP), fused in sarcoma/translocated in liposarcoma (FUS/TLS), and C9ORF72 repeat expansions." (PMID 35455952, 2022). "Currently, it is accepted that superoxide dismutase 1 (SOD1) and TAR DNA-binding protein 43 (TDP-43), fused in sarcoma/translocated in sarcoma (FUS) and chromosome 9 open reading frame 72 (C9ORF72), are the main contents of the neuronal inclusions." (PMID 35479082, 2022). "Cu/Zn-superoxide dismutase (SOD1), TAR DNA-binding protein of 43kDa (TDP-43), fused in sarcoma/ translocated in liposarcoma (FUS/TLS), and vesicle-associated membrane protein-associated protein B (VAPB) are genetic factors in patients with ALS." (PMID 35765969, 2022). "In 11 patients, six had phosphorylated TAR DNA-binding protein 43 (pTDP-43)-immunoreactive (ir) neuronal cytoplasmic inclusions (NCI), two had fused in sarcoma (FUS)-ir NCI, and three had copper/zinc superoxide dismutase (SOD1)-ir NCI." (PMID 27716404, 2016). "Previous ALS mouse models include ones involving the SOD1, TDP-43 as well as the DNA/RNA binding proteins FUS (fused in sarcoma) genes." (PMID 23029473, 2012).
sarcoma (continued). "These genes encode a variety of proteins, such as the antioxidant enzyme Cu/Zn superoxide dismutase (SOD1), and the RNA processing regulatory factors TAR DNA binding protein 43 (TDP-43) and fused in sarcoma/translocated in liposarcoma (FUS/TLS)." (PMID 22547957, 2011). "ALS models are commonly based on mutant superoxide dismutase 1 (SOD1), TAR DNA-binding protein 43 (TDP-43), fused in sarcoma or translocated in liposarcoma (FUS), the chromosome 9 open reading frame 72 (C9orf72) gene, ubiquilin 2 (UBQLN2), matrin 3 (MATR3), and senataxin (SETX)." (PMID 36672187, 2023). "In particular, mutations in several genes including superoxide dismutase 1 (SOD1), TAR DNA-binding protein-43 (TDP-43), fused in sarcoma/translocated in liposarcoma (FUS/TLC), and/or C9orf72, are thought to contribute to the progressive degeneration of motor neurons." (PMID 29872373, 2018). "However, there is also significant pathological heterogeneity: ALS caused by mutations in the SOD1 (Cu-Zn superoxide dismutase) and FUS (fused in sarcoma) genes does not involve TDP-43 proteinopathy, although cytoplasmic protein aggregates of varying composition are present." (PMID 39409162, 2024).
gastric ulcer (60 papers, 2007 to 2026). An ulcerated lesion in the mucosal surface of the stomach. "Oxidative stress in gastric ulcers was determined by measuring the levels of SOD-1 and GSH, which are antioxidant-acting enzymes in gastric tissues, and MDA, which is a lipid peroxidation product." (PMID 41036937, 2025).
asthma (59 papers, 2009 to 2025). "The H2O2-poly(I:C) co-stimulation dose-dependently reduced gene and protein levels of SOD2 and partially SOD1, thus mimicking clinical findings of antioxidant deficiency at asthma exacerbation." (PMID 31849956, 2019). "miR-206 can target the 3′-UTR of SOD1 to inhibit SOD1 expression, which leads to the increase in ROS level and aggravates the pulmonary inflammatory response and asthma symptoms." (PMID 39997934, 2025). "In asthmatic mice, miR-206 can target the 3′-UTR of SOD1 and inhibit its expression, aggravated lung inflammation and asthma symptoms." (PMID 37593445, 2023). "This appears to extend to the bronchial inflammation disease asthma, where the wild-type SOD1 disulphide is reduced as a result of an imbalanced oxidized/reduced glutathione ratio." (PMID 29703933, 2018). "SOD1 is also observed to be disulphide reduced in people living with asthma." (PMID 29703933, 2018). "Besides, the expression of SOD1 was notably increased in asthma+ FMT 20 mg/kg group mice." (PMID 33013383, 2020). "Here we have shown that ebselen has astonishing capacities for correcting several aspects of aberrant mutant SOD1 maturation with implications for the treatment of ALS and asthma." (PMID 29703933, 2018). "However, compared with asthma group, the asthma + FMT 40 mg/kg group mice showed a robust increase in the expression of SOD1 and HO-1." (PMID 33013383, 2020). "The results demonstrated that the expressions of Nrf2 and SOD1 were slightly decreased while the expression of HO-1 was moderately increased in asthma group mice compared with control group, but there were not statistical significance." (PMID 33013383, 2020). "If the reversibility of ebselen binding can be fine-tuned through rational structurally informed design, the implication is that SOD1’s toxic characteristics could be modulated in vivo over long time-courses for the treatment of ALS and asthma without damaging our response to oxidative stress." (PMID 29703933, 2018).
hepatocellular carcinoma (59 papers, 2008 to 2025). A malignant tumor that arises from hepatocytes. "For example, mice deficient in SOD1 have been shown to develop hepatocellular carcinomas." (PMID 26569310, 2015). "Remarkably, a genetic whole-body deficiency of SOD1 only led to spontaneous nodular liver hyperplasia or hepatocellular carcinoma by 20 months of age which could be caused by the capacity of normal cells to switch to alternative ways of maintaining redox homeostasis." (PMID 39187509, 2024). "We previously reported that SOD1-deficient mice showed the accumulation of oxidative molecules and several age-related pathological changes, including macular degeneration, hemolytic anemia with splenomegaly, osteopenia, skin atrophy, skeletal muscle atrophy, hepatic carcinoma, and fatty liver." (PMID 33805584, 2021). "A high percentage (68%) of Sod1−/− mice revealed nodular hyperplasia or hepatocellular carcinoma by 20 months of age, whereas DKO mice showed the early detection of tumor formation (by 4 months) with a high probability (50%)." (PMID 33805584, 2021). "On the other hand, alteration in expression levels of SOD1 was reported when human hepatoma cell line (HepG2-C8) was exposed to some common phytochemicals present in cruciferous vegetables." (PMID 29165112, 2017). "As a result, Sod1D83G/D83G mice also phenocopy the distal axonopathy and hepatocellular carcinoma found in Sod1 null mice (Sod1−/−)." (PMID 25468678, 2015). "They showed that long term effects of CuZnSOD deficiency in mutant mice lead to widespread oxidative DNA damage which leads to cell injury, cell death, perturbance in cellular homeostasis and eventually to the development of hepatocellular carcinoma in more than 70% Sod1-/- mice." (PMID 35594248, 2022). "We investigated whether Lp(a) alone could promote changes in the antioxidant enzymes, GPx1, Prdx6, and Sod1, by incubating purified Lp(a) with human hepatoma cells." (PMID 30596094, 2018). "Of note, mice ablated with SOD1 were shown to have a decreased survival rate with increased neoplastic alterations in the liver, and about 70% of these SOD1(−/−) mice developed hepatocellular carcinoma (HCC)." (PMID 41154722, 2025). "In THLE-2, immortalized normal hepatocytes treated with these conjugates resulted in the activation of Nrf2 and increased expression in SOD-1 and NQO1, while the opposite effect was observed in the HepG2 hepatoma cells." (PMID 34358114, 2021). "While SOD1 knockout mice exhibit 30% shorter lifespan, the fact that their major cause of death is hepatocellular carcinoma and the absence of lifespan reduction in SOD1 heterozygous mice suggest the shorten lifespan in SOD1 knockout may not be due to accelerated aging." (PMID 24860647, 2014). "GPX1, SOD1, and CAT convert superoxide radicals (O2•−) produced in the mitochondrial respiratory chain into O2 and H2O, while PGLS inhibits the expression of ROS in human hepatocellular carcinoma cells, thereby inducing apoptosis." (PMID 38731375, 2024). "Immunoblot analysis showed that rHDGF treatment induced SOD2 upregulation in a dose-dependent manner but did not affect SOD1 protein levels in hepatoma cells." (PMID 37827291, 2023). "The mechanobiology of oxidative stress-related genes (i.e., catalase; superoxide dismutase 1, SOD1; and glutathione peroxidase 1, GPx-1) upon exposure to pure AgNPs in human hepatoma cells has been studied; these genes have been found to be implicated in maintaining antioxidant defense capacity." (PMID 32178476, 2020). "Examples of these include Cu/Zn-superoxide dismutase (SOD1) mutant-induced motoneuronal cell death, Cisplatin-induced apoptosis in NIH3T3 cells, UV-induced apoptosis in COS-1 cells, TIPE1- induced apoptosis in hepatocellular carcinoma cells, and TNF-α-induced apoptosis in endothelial cells." (PMID 29321004, 2018).
endothelial dysfunction (58 papers, 2009 to 2026). In vascular diseases, endothelial dysfunction is a systemic pathological state of the endothelium (the inner lining of blood vessels) and can be broadly defined as an imbalance between vasodilating and vasoconstricting substances produced by (or acting on) the endothelium. "SOD1 deficiency is also associated with increased vascular superoxide levels and endothelial dysfunction." (PMID 33080110, 2020). "Collectively, these data demonstrate a combined effect of the hyperhomocysteinemic diet and SOD1 deficiency on endothelial dysfunction that parallels the effects of diet and genotype on vascular superoxide." (PMID 28414812, 2017). "The clear additive effects of SOD1 deficiency and the hyperhomocysteinemic HM/LF diet on endothelial dysfunction suggests that, in addition to superoxide, other factors also may contribute to impaired endothelium-dependent vasodilatation." (PMID 28414812, 2017). "Indeed, in mice with a genetic ablation of the cytosolic isoform SOD1, endothelial dysfunction was associated with increased superoxide and peroxynitrite levels compared with wild type controls." (PMID 24719887, 2014). "Indeed, in mice with a genetic ablation of the cytosolic Cu/Zn-containing isoform, SOD1, endothelial dysfunction was associated with increased superoxide and peroxynitrite levels compared with wild type controls." (PMID 22013533, 2012). "SOD1 and MTHFR are linked to oxidative stress and endothelial dysfunction, indicating their role in neurovascular injury." (PMID 41032496, 2025). "A previous study found that anagliptin, a dipeptidyl peptidase IV (DPP-4) inhibitor, suppresses IH by preventing endothelial dysfunction and regulating SOD-1/RhoA/Jun N-terminal kinase- (JNK-) mediated EC migration following balloon-induced injury." (PMID 35450412, 2022). "Upregulation of SOD-1 protects against endothelial dysfunction and ischemic damage." (PMID 30647815, 2018). "In agreement with our results, recent reports have documented a marked endothelial dysfunction associated with a significant vascular pro-oxidant condition in HFD animals, as well as a decreased SOD1 scavenging activity." (PMID 30319424, 2018). "Meanwhile, in recent similar research work on SOD1 and SOD3 gene transferring indicated that adenoviral-mediated gene transfer of SOD3, but not SOD1, could improve endothelial-dependent relaxation and protect the aorta from xanthine/ xanthine oxidase-mediated endothelial dysfunction." (PMID 30140407, 2018). "Although endothelial dysfunction (ED), assessed through FMD and circulating 5-HT levels, is more pronounced in diabetic patients compared to non-diabetic patients, the circulating levels of SOD-1 and LOX-1, which reflect oxidative stress, are not influenced by T2DM in patients with severe CAD." (PMID 39859119, 2025).
pulmonary fibrosis (57 papers, 2005 to 2026). Chronic progressive interstitial lung disorder characterized by the replacement of the lung tissue by connective tissue, leading to progressive dyspnea, respiratory failure, or right heart failure. "•Ascorbic acid deficiency leads to pulmonary fibrosis in Sod1-and Akr1a-double knockout mice." (PMID 40616948, 2025). "Macrophages from patients who had been exposed to asbestos have high levels of the copper, zinc-SOD/SOD1, and produce high levels of H2O2, while SOD1−/− mice were protected from developing pulmonary fibrosis following intratracheal exposure to asbestos." (PMID 33926483, 2021). "By analyzing the target interaction network VCAM1,RELA,CDK2,JUN,CDK1,HSP90AA1,NOS2, SOD1,CASP3,AHSA1, PTGER3 are at the core of the network, which can be regarded as the key targets of Astragalus polysaccharides in treating pulmonary fibrosis." (PMID 35370663, 2022). "In comparison to the neutrophilic cases, the IPA analysis of the proteomic datasets derived from horses with metachromatic inflammation revealed enrichment in pathways related to hypersensitivity reaction (CD44, ICAM1, SOD1, PSAP, CDH1) and lung fibrosis (AGER, TGFBR2, FBLN1, S100A9)." (PMID 39594673, 2024). "Reduced the levels of caspase-3, IL-1β, TNF-α, TGF-β, HYP, 3-NT, and 4-HNE; increased the levels of Nrf2, HO−1, NQO1, SOD1, and CAT; alleviated BLM-induced alveolar epithelial cell apoptosis, alveolitis, collagen accumulation, lung oxidative stress, and lung fibrosis." (PMID 36139759, 2022).